VDR (vitamin D receptor)
Diseases named in the same sentence as VDR in open-access papers (continued):
Sharing a sentence is not in itself a finding about the gene and the disease.
Obesity (continued). "This study aimed to evaluate the impact of vitamin D supplementation and probiotics on the vitamin D receptor (VDR) levels and the gut microbiota of rats given a high-fat diet as an experimental model of obesity." (PMID 42255705, 2026). "We report the downregulation of serum VDR levels and serum 25-hydroxy vitamin D levels in people with obesity." (PMID 41264635, 2025). "Serum VDR level was downregulated in people with obesity compared to healthy controls (P < 0.0001) along with significantly lower levels of 25-hydroxy vitamin D (P < 0.0001)." (PMID 41264635, 2025). "Future studies are warranted to define optimal strategies for harnessing the VD/VDR axis in therapeutic approaches to obesity and metabolic disease." (PMID 41226298, 2025). "The mean serum vitamin D receptor (VDR) levels in the people with obesity group were 2.51 ± 0.35 ng/ml, while the control group exhibited higher levels, with a mean of 5.14 ± 0.45 ng/ml." (PMID 41264635, 2025). "The progression from physiological to dysfunctional adipose tissue in obesity is closely tied to the disruption of VD and VDR functions." (PMID 41226298, 2025). "The purpose of this study was to investigate serum VDR levels and serum 25-hydroxy vitamin D level in those with obesity and healthy controls." (PMID 41264635, 2025). "VDR belongs to the steroid hormone receptor superfamily, and it has been found to play a significant role in the development of obesity." (PMID 39045947, 2024). "Regarding energy metabolism, mice with targeted expression of human VDR in adipocytes develop obesity, due to reduced energy expenditure." (PMID 38732514, 2024). "The observed changes in other genes like VDR, IL-6, and NF-κB, although moderate, reinforce the idea that obesity affects multiple facets of the immune response." (PMID 39062991, 2024). "The response of SAT to 1,25 (OH)2D3 treatment and the expression of the VDR vary depending on the degree of obesity." (PMID 38004226, 2023). "After stimulation with 1,25(OH)2D, VDR expression is increased in the adipose tissues of individuals with obesity, and it is also higher in the visceral preadipocytes of these individuals during the differentiation process." (PMID 37233644, 2023). "Deletion of VDR in mouse intestine resulted in protection against diet-induced obesity, hepatosteatosis, and metabolic inflammation in liver and adipose tissue." (PMID 37175993, 2023). "Systemic VDR-null mice display diminished adipose tissue mass, augmented overall energy expenditure, and resistance to high-fat diet-induced obesity, which coincides with notable enhancements in glucose tolerance and insulin sensitivity." (PMID 38004226, 2023). "In our Obesity Biobank cohort study, we found that VDR gene expression significantly varied between fat depots." (PMID 37063318, 2023). "Gene-specific hypermethylation in the CYP2R1, CYP27B1, and VDR genes was observed in the obesity-induced mice." (PMID 37184736, 2023). "High energy expenditure, as seen in VDR knockout mice, is contrary to the findings of the majority of human studies that show an inverse correlation between adiposity/obesity and vitamin D status." (PMID 36815991, 2023). "Mice mutant for VDR are protected from HFD-induced obesity, inflammation and liver disease, and show decreased lipid uptake, decreased lipase activity, and a trend towards increased food intake, each reminiscent of mifepristone effects in Drosophila." (PMID 38127988, 2023). "This study shows that in both viral and genetic models, male mice with obesity and PVH VDR loss have impaired glucose tolerance while female mice are unaffected." (PMID 35620386, 2022). "In the current study, the impact of three SNPs in VDR gene (rs2228570 (FokI), rs1544410 (BsmI), rs731236 (TaqI)) on the vitamin D status and obesity marker changes after the 3-month intervention was investigated." (PMID 35308505, 2022).
Obesity (continued). "evidence that; obesity and osteoporosis share some common genetic determinations and the fact that the VDR is widely distributed, is controlling genes related to bone metabolism, chronic diseases, and inflammation." (PMID 34351532, 2021). "On the other hand, many studies supported the possibility that the vitamin D/vitamin D receptor system contributes to the development of obesity by modulating adipocyte differentiation and lipid metabolism." (PMID 34620118, 2021). "Convincing experimental data show that the vitamin D/VDR axis is directly involved in the modulation of metabolic and inflammatory pathways associated with the development of MAFLD in overweight and obesity." (PMID 33126575, 2020). "Allelic differences in the VDR gene have also shown to be possible contributors to obesity through modulating adipocyte function and affecting adipocyte inflammation." (PMID 33553043, 2020). "A likely connection between vitamin D receptor (VDR) polymorphisms and the risk of obesity has been suggested, though contradictions still exist even in this regard." (PMID 32534577, 2020). "Accordingly, the present results confirmed the molecular aspect of VDR- NFκB signaling and upregulation of VDR expression to mediate 25-OH-D3 effects in the chicken model of obesity." (PMID 33171670, 2020). "Of note, AT VDR expression levels are increased in human and experimentally-induced obesity independently from overall vitamin D status." (PMID 33126575, 2020). "All these miRNAs were found to participate in the regulation of VDR expression in vitro, and their expression is decreased in visceral adipose tissue in obesity." (PMID 31652924, 2019). "Multiple logistic regression, linear regression and general multifactor dimensionality reduction (GMDR) were performed to analyze the correlation of VDR gene and obesity indexes." (PMID 30975133, 2019). "The action of vitamin D is mediated through vitamin D receptor, a nuclear transcription-regulating factor that regulates de novo lipid synthesis, thereby contributing to the development of obesity." (PMID 30975133, 2019). "In the present study, we investigated the effect of the external environment and inherent variations of VDR on obesity-related traits in humans." (PMID 30975133, 2019). "Our results regarding the obesity-related increased expression of VDR in adipose tissues are coherent with data from previous studies in morbidly obese individuals." (PMID 31652924, 2019). "Previous preclinical studies in rodent models are partially controversial with regard to the metabolic effects of vitamin D/VDR on obesity and NAFLD." (PMID 30609782, 2019). "Paradoxically, VDR knockdown in adipocytes inhibited adipogenesis and VDR knockout mice showed less body fat and were resistant to diet-induced obesity." (PMID 31842274, 2019). "The focus of this review is the novel roles of vitamin D/VDR signaling in regulating inflammation and the microbiome, especially in obesity." (PMID 30828578, 2018). "Low serum vitamin D is correlated with obesity and insulin resistance, and many studies have identified roles for VDR in regulating metabolism." (PMID 30828578, 2018). "In this study, we investigated the genetic link between the SNPs rs9939609 of FTO and rs1544410 of VDR genes with the obesity phenotype in the Emirati population for the first time." (PMID 29343214, 2018). "Two of these genes are the Vitamin D receptor (VDR) gene and the fat mass and obesity associated (FTO) gene." (PMID 29343214, 2018). "The increase in VAT 1α-hydroxylase has already been observed in other models of obesity programming, i.e., those in which a reduction of VDR is also present, suggesting a resistance to vitamin D action." (PMID 30304827, 2018). "The mechanism by which the unliganded and liganded VDR regulate adipogenesis will provide further insight into the role of the vitamin D signaling pathway in obesity." (PMID 29112142, 2017).
Obesity (continued). "Our functional studies by EMSA suggested that the differential expression pattern of IGFBP-3 in obesity is regulated by higher expression of the VDR in HIR-MO and LIR-MO, respectively, in adipose tissue." (PMID 29112142, 2017). "Several studies attempted to link variability in VDR region with obesity and adiposity traits on smaller population samples." (PMID 28830368, 2017). "Reports regarding VD3 and obesity have been contradictory; for example, VDR knock-out mice are resistant to high-fat diets-induced weight gain and show a slower growth rate and accumulate less fat mass." (PMID 27473111, 2016). "Results herein reinforce the concept that the vitamin D/VDR axis plays a role in obesity which is at least partially mediated by an ongoing degree of inflammation." (PMID 25020064, 2014). "VDR haplotypes identified are positively (GTA) (p = 0.008, β = 1.560); or negatively (ACC) (p = 0.044, β = 0.766) associated with obesity and higher BMI scores." (PMID 25020064, 2014). "In one study, transgenic mice with targeted expression of human VDR in the adipose tissue developed obesity due to reduced energy expenditure." (PMID 23800102, 2013). "Wong and colleagues by study on transgenic mice, showed that the prevalence of obesity was higher in mice with modified VDR (vitamin D receptor) compared to normal mice as a result of decreased REE and β-oxidation of fatty acids." (PMID 23497722, 2012). "First, genetic polymorphisms in the vitamin D receptor, insulin-induced gene 2 (INSIG2), and FTO genes (fat mass and obesity associated genes) have been linked to obesity and metabolic disorders." (PMID 18335103, 2008). "Moreover, we looked at serum VDR levels and serum 25-hydroxy vitamin D levels in people with obesity (n = 124) and healthy controls (n = 126)." (PMID 41264635, 2025). "Furthermore, we found that serum VDR levels were considerably lower in the people with obesity group compared to the healthy control group (P < 0.001)." (PMID 41264635, 2025). "In contrast, VDR and peroxisome proliferator-activated receptor γ mRNA are upregulated in the adipose tissue of GDM women, particularly in overweight or obese cases, indicating that obesity may amplify VDR expression." (PMID 41007445, 2025). "Decreased VDR levels in people with obesity might be the result of compromised receptor-mediated signaling, which could worsen the negative effects of vitamin D insufficiency on metabolic health." (PMID 41264635, 2025). "Overexpression of VDR leads to reduced energy expenditure and results in obesity in mice models." (PMID 41264635, 2025). "Serum VDR and 25-hydroxy vitamin D levels were downregulated in people with obesity." (PMID 41264635, 2025). "Recent studies on PPARG signaling examine connections between obesity, cancer, and the vitamin D/VDR system, introducing new research hypotheses in this area." (PMID 40334012, 2025). "In contrast, elocalcitol, a 1-α-fluor-substituted, non-hypercalcemic vitamin D derivative, has about 10 times lower efficacy for VDR, and, therefore, it is reasonable to propose that the preventive action of elocalcitol on obesity is mediated via targets other than the VDR." (PMID 39898321, 2024). "In 2009, several studies delved into VDR functionality within adipose tissue and its impact on energy metabolism and inflammation, shedding further light on the connection between vitamin D and obesity." (PMID 39092232, 2024). "Moreover, it was suggested that VDR expression is increased in people with obesity, who have more VAT than lean subjects, but the physiological relevance of this upregulation has not yet been elucidated." (PMID 37063318, 2023). "A study from Iran which looked at the association of the VDR gene ApaI, BsmI, and TaqI polymorphisms with obesity in 348 obese and 320 non-obese subjects reported an increased risk of obesity in subjects with VDR ApaI polymorphism." (PMID 37189820, 2023).
Obesity (continued). "This association may be explained by a genetic link between vitamin D and obesity, for example, the vitamin D receptor gene." (PMID 38201869, 2023). "VDR knockout mice are lean and resistant to diet-induced obesity due to increase in energy metabolism, suggesting that adipogenesis could be impacted." (PMID 37063318, 2023). "In addition to T2DM, obesity, and CVD, GDM progression to DM is described as a multifactorial and metabolic disorder characterized by carbohydrate intolerance, and SNPs in the VDR gene can influence the susceptibility of pregnant women to GDM." (PMID 37836571, 2023). "In obesity and vitamin D metabolism-related gene networks, vitamin D receptor (VDR), cytochrome P450 gene family, i.e., CYP2R1, CYP24A1, and CYP27B1, are key players in vitamin D metabolism and interconnected with energy balance, adipocyte physiology, and adipokine secretion." (PMID 37184736, 2023). "In addition, meta-analysis studies have documented other human diseases, such as T2DM, obesity, CVD, and polycystic ovary syndrome (PCOS), which are all risk factors for GDM and showed associations with specific SNPs in the VDR gene." (PMID 37836571, 2023). "Notably, vitamin D-metabolizing enzymes and VDR expression were different between lean subjects and those with obesity and between SAT and VAT." (PMID 35893929, 2022). "Obesity is linked to disorders of FXR and VDR, as well as TGR5 pathways in a number of cases." (PMID 36431930, 2022). "In turn, when we inhibited IRF7 expression with VDR activation and transfected adipocytes with mtRNA, we could effectively induce beige adipogenesis and mitigate obesity in mice." (PMID 36443525, 2022). "Genetic variations of vitamin D-binding protein and VDR have been associated with insulin resistance in different populations independent of obesity." (PMID 36147626, 2022). "The increase in the number of fat cells largely occurs during the fetal growth and early infancy period, leading to adverse health outcomes of obesity.Vitamin D and its receptor (VDR) have been found to influence adipocyte procreation, as VDR are present abundantly on adipocyte cells." (PMID 36249984, 2022). "This genomic effect of VD through VDR is strongly suspected to drive a large share of the biological effects of VD in health and disease, notably in the context of obesity, based on evidence from several studies that point to a correlation between VDR polymorphism and pathological issues." (PMID 35631190, 2022). "We hypothesized that optimization of VD status can attenuate the obesity-induced colonic inflammation through the activation of VDR in the gut." (PMID 36557290, 2022). "Ruiz-Ojeda and his colleagues hypothesized that allelic variations in the VDR gene might be potential participators in obesity pathophysiology through alternating adipocyte function and increasing adipocyte inflammation association." (PMID 34351532, 2021). "Four studies have investigated other VDR SNPs; of which, two have shown significant association, while the other two failed to report a significant association with obesity traits." (PMID 33553043, 2020). "We studied the effect of obesity on VDR expression in different mouse tissues." (PMID 33210060, 2020). "In mice, obesity repressed expression of the vitamin D receptor in brown adipose tissue." (PMID 33210060, 2020). "The dysfunction of the VDR-associated bile acid pathway observed in our study further explains the risk of HFD-induced obesity without the protection of Vitamin D/VDR." (PMID 32355205, 2020). "Results regarding VDR and obesity are numerous but conflicting." (PMID 32534577, 2020). "Next, the observed negative correlations between VDR mRNA level and expression of the selected miRNAs in obese study participants were limited to the visceral adipose tissue depot, and do not explain obesity-associated changes in VDR expression in SAT." (PMID 31652924, 2019).
Obesity (continued). "In contrast with our findings, in a randomized control trial of 60 type 2 diabetic patients, results showed that vitamin D supplementation (25 μg/d) decreased obesity indices, including WC, body fat mass and truncal fat, only in individuals with the AA genotype of Cdx2 VDR." (PMID 31395070, 2019). "It hence seems reasonable to hypothesize that genetic variations within the VDR gene could alter the individual’s response to vitamin D3 supplementation in terms of obesity and metabolic status." (PMID 31395070, 2019). "The data demonstrated that lower 25(OH)D levels are associated with T2DM, which are not influenced by obesity status and VDR gene polymorphisms (ApaI, BsmI, FokI, and TaqI)." (PMID 31121922, 2019). "In conclusion, our results suggest that Brazilian T2DM patients presented lower plasma 25(OH)D levels, which were not affected by obesity and polymorphisms in the VDR gene." (PMID 31121922, 2019). "Furthermore, we extend our discussion of potential gut-liver axis mediated by VDR signaling and microbiota in obesity." (PMID 30828578, 2018). "Dysregulation of vitamin D/VDR might lead to increased gut permeability, bacterial translocation, and obesity." (PMID 30828578, 2018). "However, data from non-PCOS populations suggest that metabolic abnormalities, such as obesity, insulin resistance, low HDL-c, and type 2 diabetes are associated with the VDR gene." (PMID 29669566, 2018). "Afterwards, possible links between four interrelated actors will be established: PPARG, the vitamin D/VDR system, obesity, and cancer, opening up the door to further investigation and new hypothesis in this fascinating area of research." (PMID 27579030, 2016). "Derived from these observations, we have coined the so-called “nuclear receptor exhaustion theory,” by which, in an early disease stage, nuclear receptors PPARG and VDR counterbalance the harmful effects that obesity and cancer exert upon the organism, their expression being high." (PMID 27579030, 2016). "In conclusion, results herein reinforce the idea that the vitamin D/VDR axis plays a role in the pathogenesis of obesity that is dependent on the presence of particular SNP and is at least in part mediated by an ongoing degree of inflammation, possibly secondarily to microbial translocation." (PMID 25020064, 2014). "As VDR modulates inflammation, which in turn is observed in obesity, we verified whether the VDR SNPs that are more common in obese individuals would be associated with an up-regulation of inflammosome-related proteins and cytokines." (PMID 25020064, 2014). "One of the main evidence for a role of VDR in obesity was derived from transgenic mice studies that over-express human VDR in adipocytes which leads to a marked decreases in energy expenditure and induction of obesity." (PMID 25020064, 2014). "Besides being involved in the pathogenesis of obesity, the vitamin D/VDR axis also modulates inflammation." (PMID 25020064, 2014). "Results of these analyses showed that the VDR rs731236 (G) and VDR rs1544410 (T) alleles were positively associated with BMI and these alleles were associated with obesity independent of age and sex (p = 0.009, β = 0.086 and p = 0.028, β = 0.072 respectively)." (PMID 25020064, 2014). "To explore the mechanisms underlying the suggested role of the vitamin D/vitamin D receptor (VDR) complex in the pathogenesis of obesity we performed genetic and immunologic analyses in obese and non-obese Saudi individuals without other concomitant chronic diseases." (PMID 25020064, 2014). "Studies in vitamin D receptor (VDR) knockout mice revealed a lean phenotype resistant to diet-induced obesity, suggesting that vitamin D may have a role in promoting adipose tissue development in an in vivo context." (PMID 24369921, 2013).